LINC00210 (long independently transcribed non-coding RNA 210)
Synonyms: RP11-72L13.1; NCRNA00210
Gene: Long non-coding RNA gene on chromosome 1 (217,892,900 to 217,920,804, forward strand). Ensembl gene ENSG00000231814.
Diseases named in the same sentence as LINC00210 in open-access papers:
LINC00210 is named in the same sentence as 4 diseases in open-access papers, as found by Europe PMC text mining. Sharing a sentence is not in itself a finding about the gene and the disease. The quoted sentences say what the papers report.
cancer (1 paper, 2018). A tumor composed of atypical neoplastic, often pleomorphic cells that invade other tissues. "Whether LINC00210 is implicated in other cancer requires investigation." (PMID 30341249, 2018). "Knockdown of LINC00210 dramatically inhibited NPC cell proliferation and invasion in vitro and impaired cancer growth in vivo." (PMID 30341249, 2018).
tumor (1 paper, 2018). "Based on functional experiments, we revealed that LINC00210 contributed to NPC cell proliferation and invasion in vitro, and promotes tumor growth in vivo." (PMID 30341249, 2018). "Our study demonstrated that LINC00210 facilitates NPC progression, and correlates with tumor metastasis and prognosis." (PMID 30341249, 2018). "However, our work did not elucidate the mechanisms of LINC00210 induction and how LINC00210 expressions are regulated in normal and tumor tissues." (PMID 30341249, 2018).
LINC00210 also shares sentences with these, for which no sentence is quoted: nasopharyngeal carcinoma (1 paper); osteosarcoma (1).